CDK12 (cyclin dependent kinase 12)
Diseases named in the same sentence as CDK12 in open-access papers (continued):
Sharing a sentence is not in itself a finding about the gene and the disease.
breast carcinoma (continued). "Based on our results, JWA plays a crucial role in HER2+ trastuzumab-resistant breast cancer by controlling CDK12 expression." (PMID 34686673, 2021). "Among the 12 breast cancer patients, CDK12 was highly expressed in eight patients and moderately expressed in four patients." (PMID 34686673, 2021). "CDK12 is associated with the expression of DNA damage response (DDR) genes and has been considered as a drug target for HER2+ breast cancer." (PMID 34686673, 2021). "In breast cancer cells, CDK12 is frequently amplified together with its neighbouring HER2 gene and it was shown to drive tumour initiation and progression by activating signaling pathways that promote self‐renewal of cancer stem cells." (PMID 34092037, 2021). "Survival analysis of the HER2+ breast cancer patients showed that the survival time of patients with high expression of CDK12 was significantly lower than that of patients with low expression, with the difference being statistically significant (P = 0.0074)." (PMID 34686673, 2021). "To gain insight into the underlying mechanism of JWA in trastuzumab-resistant breast cancer, we found that overexpression of JWA significantly downregulated CDK12 levels in JIMT1 and BT474-Tr cells." (PMID 34686673, 2021). "In HER2-enriched breast cancer, CDK12 promotes tumor initiation and trastuzumab resistance, while CDK12 inhibition enhances the efficacy of trastuzumab." (PMID 33686962, 2021). "Our study also showed that CDK12 expression was decreased after JWA overexpression in breast cancer cells or tissues." (PMID 34686673, 2021). "Breast cancer microarray data (GSE19615) revealed that high expression of JWA was correlated with low levels of CDK12 in breast cancer." (PMID 34686673, 2021). "To investigate the functional roles of CDK12 in trastuzumab-resistant breast cancer progression, we knocked down CDK12 via two independent siRNAs in JIMT1 and BT474-Tr cells." (PMID 34686673, 2021). "In summary, CDK12 acts as tumor promoter in HER2-positive breast cancer, but as a tumor suppressor in TNBC." (PMID 32570740, 2020). "High expression of CDK12 is associated with HER2 status and plays important roles during the tumorigenesis and development of breast cancer." (PMID 32570740, 2020). "CDK12 mutations were identified in 1.5% of TNBC patients, and the gene disruption was found in 13% of HER2+ breast cancer." (PMID 32235451, 2020). "In most HER2 (ERBB2)-positive breast cancers, there is a significant correlation between CDK12 overexpression and tumor aggressiveness." (PMID 32451425, 2020). "The resulting increased expression of CDK12 mRNA and protein accompanied by increased phosphorylation of CDK12 was suggested to drive the oncogenic activities of CDK12 in this type of breast cancer." (PMID 34316683, 2020). "In breast cancer cells, ALE splicing by CDK12 regulates the expression of DDR activator ATM and DNAJB6 isoforms, which can influence tumorigenesis when CDK12 is mutated or silenced." (PMID 32451425, 2020). "It is worth noting that HER2-positive breast cancers are mutually exclusive with breast tumours carrying mutations in BRCA1, which is consistent with the incompatibility of overexpressed CDK12 during the genesis of HR-defective tumours." (PMID 34316683, 2020).
breast carcinoma (continued). "We then sought to investigate the prevalence of CDK12 c.1047-2A>G in populations beyond the Tatars and performed a replication study in patients of Bashkir ancestry, also selected from the Hannover-Ufa Breast Cancer Study." (PMID 31259151, 2019). "Cyclin-dependent kinase 12 (CDK12) amplification in breast cancer results in downregulation of MRJ-L via modulating its terminal exon selection." (PMID 31921062, 2019). "For example, RALY and SNW1 stimulate exon 2 inclusion in PRMT1, promoting breast cancer invasiveness and CDK12 promote alternative last exon splicing of DNA damage genes ATM and DNAJB6 thereby increasing migration and invasiveness of breast cancer cells." (PMID 31666932, 2019). "Depletion of CDK12 in breast cancer cells resulted in accumulation of DNAJB6 long isoform, thereby decreasing the migration and invasion abilities of MDA-MB-231 cells." (PMID 31523177, 2019). "They found that CKD12 is upregulated in HER2–positive breast cancer samples and demonstrated a strong correlation between CDK12 level and high tumor grade." (PMID 29090014, 2017). "Mertins and colleagues analyzed the proteome of breast cancer samples and found CDK12 amplification on mRNA and protein level as well as increased CDK12 phosphorylation in HER2-amplified tumors." (PMID 29090014, 2017). "Several pieces of evidence also point to an important role for Cdk12 in the development of breast cancer." (PMID 22512864, 2012). "Moreover, a higher number of tumorigenic CD44+ cells in the CDK12 high group indicates that CDK12 promotes the preservation of breast cancer stemness and is connected to lung metastases." (PMID 40361480, 2025). "ERBB2/CDK12 co-amplification may be a potential biomarker for favorable responses in HER2-positive breast cancer." (PMID 39806366, 2025). "Additionally, CDK12 promotes breast cancer stemness and metastasis by activating oncogenic pathways such as c-myc/β-catenin, further driving tumorigenicity and therapy resistance." (PMID 39806366, 2025). "The findings suggest that amplifications in cell cycle-related genes may confer primary resistance in HER2-low cancers, while ERBB2/CDK12 co-amplification appears to be a promising marker for favorable response in HER2-positive breast cancer." (PMID 39806366, 2025). "The positive correlation between CDK12 and c-myc expression emphasizes its function in triggering the c-myc/β-catenin signaling pathway, which may be a mechanism promoting the renewal of breast cancer stem cells." (PMID 40361480, 2025). "Importantly, CDK12 inhibition with SR-4835 has been shown to enhance anti–PD-1 efficacy in colorectal and breast cancer models by increasing CD8+ T cell infiltration into tumors." (PMID 40996961, 2025). "Conversely, elevated CDK12 expression is seen in human malignancies such as HER2(+) breast cancer." (PMID 39368479, 2024). "In contrast, HER2 breast cancer with CDK12 enhancement is resistant to HER2+ targeted therapy." (PMID 38338997, 2024). "Moreover, growing evidence has demonstrated that CDK12 is a highly relevant gene in breast cancer development." (PMID 38503865, 2024). "Conversely, CDK12 is co-amplified with the receptor tyrosine kinase (RTK) oncogene HER2 (also known as ERBB2) in many cases of breast cancer, where it promotes migration and invasion of tumor cells by downregulation of the nuclear isoform of DNAJB6 via alternative last exon splicing." (PMID 37811895, 2023). "Interestingly, miR-613 was recently reported to similarly directly modulate paclitaxel resistance via targeting CDK12 in human breast cancer." (PMID 35455981, 2022). "The dependency of CDK12HIGH breast cancers on CDK12 overexpression was verified by silencing CDK12." (PMID 35550508, 2022).
breast carcinoma (continued). "The reversion of the poor prognostic outcome of CDK12HIGH patients, in response to CMF therapy, to a more favorable disease course similar to that observed in CDK12LOW patients reveals a typical oncogene addiction-like therapeutic vulnerability in CDK12-overexpressing breast cancers." (PMID 35550508, 2022). "Together, these results point to a scenario in which CDK12 overexpression in breast cancer cells, on the one hand, confers resistance to standard genotoxic chemotherapy, while, on the other, it introduces a selective therapeutic vulnerability through pathological rewiring of the SGOC metabolism." (PMID 35550508, 2022). "Our potent CDK12 inhibitors may serve as a good starting point in developing novel therapy for HER2+ breast cancers." (PMID 36145262, 2022). "While in WT mice the appearance of palpable mammary tumors was a rare event, which first appeared after 22 weeks post-treatment, adult CDK12-KI mice exhibited a dramatically high tumor penetrance and multiplicity rate, accompanied by a significantly decreased tumor latency and survival rate." (PMID 35550508, 2022). "It has been reported that CDK12 drives breast cancer initiation and induces trastuzumab resistance." (PMID 34686673, 2021). "Furthermore, inhibition of CDK12 activity was shown to enhance the anticancer efficacy of different HER2‐targeting treatments in HER2+ breast cancer cells." (PMID 34092037, 2021). "Furthermore, the downregulation of CDK12 in HER2+ breast cancer cells also showed sensitivity to PARPi." (PMID 32235451, 2020). "Notably, the depletion of CDK12 in three breast cancer cell lines led to differential expression of distinct genes; however, these cellular processes were confirmed to be commonly modulated by CDK12 in all three cell lines." (PMID 34316683, 2020). "For instance, in breast cancer cells, CDK12 overexpression led to altered alternative last exon splicing of a subset of genes and increased the invasiveness of a breast cancer cell line by decreasing the expression of the long isoform of DNAJB6 (Paculová and Kohoutek, 2017)." (PMID 31024625, 2019). "Moreover, SCUBE2, TMEM26, and SMOC2 were validated as subtype-specific coding genes in luminal A breast cancer, CDK12 and SDC1 in HER2 breast cancer and PSAT1 in triple negative breast cancer in TCGA and GEO datasets." (PMID 31801944, 2019). "Our study confirms a high prevalence of CDK12*c.1047-2A>G in the Tatar and Bashkir population but excludes a role as a clinically actionable high-risk breast cancer mutation." (PMID 31259151, 2019). "Thus, inhibition of both CDK1 and CDK12 by Dinaciclib seems to be important in the reversal of chemoresistance in breast cancer cells." (PMID 29686231, 2018). "In addition to HGSOC, several studies have shown dysregulation of CDK12 in individual subtypes of breast cancer." (PMID 29090014, 2017). "In addition, Her2-positive breast cancer cells with downregulated CDK12 display sensitivity to PARP1/2 inhibitors." (PMID 29090014, 2017). "In breast cancer cells, depletion or overexpression of CDK12 leads to altered alternative last exon splicing of a subset of genes and may contribute to tumorigenesis." (PMID 29090014, 2017). "Therefore CDK12 overexpression can increase the invasiveness of a breast cancer cell line, by decreasing the expression of the long isoform of DNAJB6." (PMID 29090014, 2017). "In addition, genomic disruption of CDK12 caused by out-of-frame rearrangements was found in one MPC and in 13% of HER2-positive breast cancers, identified through a re-analysis of publicly available massively parallel sequencing data." (PMID 24395524, 2014). "Next, we analyzed whether the association between CDK12 overexpression and sensitivity to MTX vs. resistance to standard chemotherapy, observed in our model systems in vitro and in vivo, was relevant to real-life breast cancer patients." (PMID 35550508, 2022).
breast carcinoma (continued). "This study may provide an insight into designing potent CDK12 inhibitors for HER2+ breast cancers." (PMID 36145262, 2022). "Finally, the mother of the case with the P1275L substitution in CDK12 suffered for breast cancer." (PMID 35347810, 2022). "Thus, our CDK12 inhibitors could be developed to treat trastuzumab-resistant HER2+ breast cancers and escalate the efficacy of trastuzumab, as well." (PMID 36145262, 2022). "Among the five samples with MMR loss for which PD-L1 was available, one (20%) had detectable PD-L1 ≥1; one of the three cyclin-dependent kinases 12 (CDK12) altered samples also had detectable PD-L1 ≥1 (33%), but none (0%) of the six breast cancer 2 (BRCA2) mutated mCRPC cases expressed PD-L1." (PMID 35491356, 2022). "Furthermore, evidence from molecular and pharmacological genetics studies in CDK12-KI/PyMT mouse tumors and human breast cancer PDX models revealed that targeting SGOC metabolism is a selective strategy to counteract CDK12-induced tumorigenesis and metastatic spreading." (PMID 35550508, 2022). "Therefore, we believe that JWA is likely to inhibit breast cancer growth by downregulating CDK12." (PMID 34686673, 2021). "However, protein expression of CDK12 was only analyzed in breast cancer." (PMID 31523177, 2019). "The CDK12 gene is located on chromosome 17q12, approximately 200 kb upstream of ERBB2 (HER2) oncogene, and is frequently co-amplified with HER2 in HER2+ breast cancers." (PMID 41491919, 2026). "Cathepsin E can mediate the effects of APBB1IP, NT5C3B, and ZNF66 on HER2-negative breast cancer, as well as the effects of DHRS9, CDK12, and CD247 on HER2-positive breast cancer." (PMID 39944834, 2025). "CDK12 influences various signaling pathways, which in turn promotes the development of HER2-positive breast cancer." (PMID 40361480, 2025). "Coamplification of the CDK12 and ERBB2 genes has previously only been reported in NST breast carcinomas; this study reports this finding for the first time in lobular breast carcinoma." (PMID 38335502, 2024). "Other clinical responders whose tumors had biallelic LOF included two patients with CRPC (somatic ATM and CDK12 alterations) and one with germline BRCA1-altered breast cancer." (PMID 37277454, 2023). "Among these was a new cell cycle checkpoint module enriched in basal breast cancer samples and a module of PRKC isozymes putatively co-regulated by CDK12 in lung cancer." (PMID 37394063, 2023). "CDK12 is involved in tumorigenesis and is assigned oncogenic functions in, e.g., HER2-positive breast cancer, as well as tumor suppressor functions in, e.g., ovarian, prostate, and triple-negative breast cancer." (PMID 38132164, 2023). "For example, CDK12 positivity was correlated with HER2 positivity; and MIEN1 overexpression facilitates migration, invasion and metastasis in breast cancer and it is negatively correlated with disease free survival mainly in HER2-positive subtypes." (PMID 37096121, 2023). "Particularly, we found a high concurrent amplification of CDK12 in HER2+ GC patients, which amplification was reported to sensitize/re‐sensitize HER2+ breast cancer to lapatinib." (PMID 38050871, 2023). "Related to this, CDK12 and CDK13 inhibition in breast cancer induces immunogenic cell death and enhances PD-1 immunotherapy, while on the other hand, defective transcriptional elongation is described to confer immunotherapy resistance for some cancers." (PMID 38132164, 2023). "To date, the CDK inhibitors (CDKIs), specifically the ones that block the enzyme activity of CDK12/13 and CDK4/6, have been validated as a promising therapeutic treatment in breast cancer." (PMID 36495130, 2023). "We previously reported that in the majority of HER2+ breast-cancer patients, CDK12 is co-amplified on 17q12 and involved in developing tumors and trastuzumab resistance, proposing CDK12 as a potential drug target for HER2+ breast cancers." (PMID 36145262, 2022).
breast carcinoma (continued). "CDK12 overexpression increases the phosphorylation of antiapoptotic proteins, including Survivin and MCL-1 and correlates with shorter overall survival in breast cancer, ovarian cancer and gastric cancer." (PMID 36248987, 2022). "There are numerous studies regarding the synergy between silencing CDK12 and PARP inhibitors or other DNA‐damaging agents, including olaparib, irinotecan in breast cancer." (PMID 36254394, 2022). "Analogous results were obtained with the CDK12 inhibitor, THZ531 which, in line with the effects observed in CDK12-OE MCF10A cells, inhibited PSAT1 and MTHFD1 expression in CDK12HIGH breast cancer cells both at the mRNA and protein level." (PMID 35550508, 2022). "The results show that CDK12 amplification was found to be a potential predictor of trastuzumab response, and suggest HER2-positive breast cancer patients with simultaneous amplification of HER2 and CDK12 can benefit from CDK12 kinase inhibition." (PMID 36276152, 2022). "The optimal compound 7f effectivelydegraded CDK12 and CDK13 with DC50 values of 2.2 and 2.1nM, respectively, in MDA-MB-231 breast cancer cells." (PMID 35938508, 2022). "This is partly because most investigations on the pro-tumorigenic role of CDK12 employed already transformed breast cancer cell lines, often bearing CDK12 and HER2 co-amplification, thus confounding the role of CDK12 as a primary oncogene." (PMID 35550508, 2022). "JWA inhibits the expression of Cyclin-dependent kinase 12 (CDK12), which participates in the transition from G1 to S phase, thus suppressing the proliferation of trastuzumab-resistant breast cancer cells, and promoting their apoptosis." (PMID 36230577, 2022). "Thus, by coupling tumor progression with metabolic reprogramming, CDK12 creates an actionable vulnerability for breast cancer therapy and might represent a suitable companion biomarker for targeted antimetabolite therapies in human breast cancers." (PMID 35550508, 2022). "We found 30d and 30e, which showed a potent in vitro activity (CDK12/cyclinK IC50 = 21 nM and 85 nM, respectively), and a potent growth-inhibitory activity against the both HER2+ breast-cancer cell lines (SK-Br3 GI50 = 46–52 nM, HCC1954 GI50 = 34–36 nM)." (PMID 36145262, 2022). "Choi reported that CDK12 is a novel regulatory factor of tumor stem cells, which can promote tumor initiation and induce anti-HER2 resistance in breast cancer." (PMID 34686673, 2021). "Thus, CDK12/CDK13 inhibitors may be a promising treatment option for breast cancer." (PMID 33686962, 2021). "The results revealed that the mRNA expression of CDK7, CDK8, CDK9, CDK10, CDK12, CDK19, and CDK20 was upregulated in patients with breast cancer." (PMID 33686962, 2021). "CDK12 is a potential carcinogenic driver and the synergistic effect of CDK12 and HER2 promotes the initiation and progression of HER2+ breast cancer." (PMID 34686673, 2021). "Overexpression of CDK12 has some properties of an oncogene in other tumors and promotes the proliferation of HER2-positive breast cancer, which results in metastasis and poor prognosis." (PMID 33628849, 2021). "In a subset (∼14%) of HER2-positive breast cancer, the HER2 amplicon breakpoint converges on CDK12, disrupting its expression and leading to sensitivity to PARPi." (PMID 34316683, 2020). "In HER2-positive breast cancer, CDK12 acts as a tumor promoter, while in TNBC, CDK12 acts as a tumor suppressor." (PMID 32570740, 2020). "In breast cancer, alternative last exon (ALS) splicing of genes with long transcripts and many exons can be regulated by CDK12." (PMID 31523177, 2019). "CDK12 amplification, resulting in its overexpression, correlates with more aggressive tumor progression in HER2-positive breast cancers." (PMID 29090014, 2017).